RNF43 (ring finger protein 43)
Diseases named in the same sentence as RNF43 in open-access papers (continued):
Sharing a sentence is not in itself a finding about the gene and the disease.
tumor (continued). "Immunohistochemical analysis of RNF43 expression in tumor biopsies obtained before the trial demonstrated abundant expression of RNF43 in 8 of the 10 patients." (PMID 29293510, 2018). "Eligible patients were resistant to standard therapy, HLA-A*24:02- or A*02:01-positive and exhibiting high RNF43 expression in their tumor cells." (PMID 29293510, 2018). "A second biopsy was gathered from a mCRC patient whose tumour carried genetic alterations in RNF43 and BRAF genes, and clinically responded and then relapsed to EGFR blockade with cetuximab in combination with the BRAF inhibitor encorafenib." (PMID 29895949, 2018). "Whole-exome sequencing of patient tumour-matched samples reveal loss-of-function (LOF) mutations to RNF43, which negatively regulate Fzd receptors, in 18.9% of CRCs, showing a higher prevalence in microsatellite instable (MSI) tumours." (PMID 29570681, 2018). "RNF43 expression was even lower in tumorspheres derived from tumor tissues or cell lines compared with adherent cancer cells and normal gastric cells." (PMID 28446252, 2017). "RNF43 was also reported as a negative regulator of the Wnt signaling pathway, which is instrumental for development and tumor carcinogenesis." (PMID 28446252, 2017). "In the RNF43 OE group, β-catenin was decreased and even lost in some regions, whereas in the control group β-catenin was relatively higher in tumor cells." (PMID 28446252, 2017). "Western blot assay and qRT-PCR demonstrated that the expression of RNF43 was lost in clinical tumorspheres compared with corresponding tumor tissues and adjacent normal tissues." (PMID 28446252, 2017). "We first examined RNF43 protein expression in GC tumor tissues and normal tissues by immunohistochemistry." (PMID 28446252, 2017). "Since R-spondin sensitizes cells to Wnt ligands through inhibiting ZNRF3/RNF43, tumor cells harboring RSPO2/RSPO3 translocations should be sensitive to either direction inhibition of RSPO2/RSPO3 or inhibition of Wnt ligand secretion by porcupine inhibitors." (PMID 27338477, 2016). "Clearly, additional studies are needed to corroborate these findings and to fully understand the function of the R-spondin-ZNRF3/RNF43 signaling module in tumor initiation, maintenance, and metastasis in various tumor types." (PMID 27338477, 2016). "As expected, RNF43 and ZNRF3 mutations tend to be mutually exclusive with APC and β-catenin mutations in those tumor types, reflecting their shared consequences in activating the Wnt/β-catenin signaling pathway." (PMID 27338477, 2016). "This highlights the potential relevance of RNF43 as a biomarker in other tumor contexts." (PMID 40735046, 2025). "We investigated whether RNF43 expression correlated with the tumor stage of patients with GC using the UALCAN database." (PMID 41487817, 2025). "High tumor mutational burden (TMB) is associated with immunotherapy, and several genes related to high TMB, including ARID1A, RNF43, BRAF, and KM2B in microsatellite instability (MSI) tumors, may also be used for the treatment of MSS patients." (PMID 40242245, 2025). "Literature data suggest the hypothesis of a possible cross-talk between MAPK and RNF43 pathways in modulating the anti-tumor activity of BRAFV600E-targeted treatments, also related to the state of microsatellites." (PMID 40735046, 2025). "Similarly, by comparing RNF43-mutant patients across tumor stages, the platform revealed a significant survival disadvantage in metastatic cases, a finding that would otherwise require multi-step analyses in standard bioinformatics tools." (PMID 40860720, 2025). "Furthermore, RNF43 appears to be a critical modulator in the tumor immune microenvironment, resulting in a promising biomarker for predicting the efficacy of immunotherapeutic regimens." (PMID 40735046, 2025). "Frequent somatic RNF43 hot spot variants combined with SBS96 signature and increased tendency to DNA methylation may contribute to tumor multiplicity in LS." (PMID 38725616, 2024).
tumor (continued). "Together, these data indicate that loss of ZNRF3 and RNF43 can promote tumor cell growth through EGFR signaling, sometimes even without substantially engaging canonical WNT signaling." (PMID 38260423, 2024). "The RNF43 variants were completely absent in the normal tissue, indicating tumor-associated mutational hotspots." (PMID 38725616, 2024). "Interestingly, we detected tcGT events with a known tumor suppressor gene RNF43 and two oncogenes ETS2 and SLCO1B3 supporting the extensive contribution of TEs during tumorigenesis." (PMID 38272908, 2024). "This study examined whether the integration of Ring finger protein 43 (RNF43) expression and CD163+ tumor‐associated macrophage (TAM) infiltration in combination with clinical indexes forecast ccRCC patient outcome with relatively high accuracy." (PMID 36097369, 2023). "Above all, RNF43 may interact with various immune-related biomolecules in different cancers, thereby regulating the tumor immune microenvironment and cancer progression." (PMID 37848933, 2023). "Since RNF43 negatively regulates the Wnt signaling pathway as a tumor suppressor, we would have expected that high expression in intestinal type GC would be associated with a less active Wnt signaling pathway and better survival compared with the diffuse type GC." (PMID 36823311, 2023). "Hence, RNF43 plays a key role in modulating the tumor immune microenvironment, and serves as a prognostic, therapeutic and immunological biomarker and a novel therapy target in clinical cancer management." (PMID 37848933, 2023). "Moreover, our recent study has demonstrated that RNF43 has been served as a tumor suppressor and prognostic biomarker in ccRCC." (PMID 36097369, 2023). "However, in this study, we only observed possible truncating driver mutations in RNF43 and APC among plasma samples at very low (<2%) allele frequency and these mutations were different than those observed in matched tumor samples." (PMID 36454217, 2023). "At the same time, in terms of unique molecular landscape, RNF43 mutant tumours seems to be immune activated and may be sensitive to Wnt-targeted agents and immunotherapy." (PMID 37409251, 2023). "However, the pan-cancer panoramic picture of RNF43 and its predictive value for tumor immune phenotypes and immunotherapeutic efficacy are still largely unclear." (PMID 37848933, 2023). "RNF43 antibodies have also been used to evaluate protein levels in tumor samples." (PMID 37023034, 2023). "Furthermore, RNF43 seems to be a critical modulator in the tumor immune microenvironment and can function as a promising biomarker for predicting the immunotherapeutic efficacy of anti-PD-1/PD-L1 treatment, and drug sensitivity in cancer treatment." (PMID 37848933, 2023). "RNF43 was positively detected in all of the examined tumor tissue samples." (PMID 37848933, 2023). "However, despite their putative tumor biological role, data on the expression of RNF43 and LRP1B in GC are scarce." (PMID 36823311, 2023). "Hence, our first and comprehensive pan-cancer research focused on the potential roles of RNF43 in predicting the prognosis, tumor immune phenotypes, and the response to immunotherapies and drug sensitivity." (PMID 37848933, 2023). "Rnf43 is a tumor suppressor in the prevention of pancreatic malignant transformation." (PMID 35229994, 2022). "As a result, a homozygous large deletion of RNF43 was found in 023‐O and matched tumor tissues." (PMID 34850547, 2022). "RNF43 inactivating mutation and KRAS activating mutation coexist in a subset of IPMN tumor tissues." (PMID 35229994, 2022).
tumor (continued). "Subcutaneous xenografted results showed that overexpressing RNF43 in RCC cells dramatically reduced the tumor size and mass when compared to the control group, while co-overexpressing RNF43 with miR-181d-5p could block the effects of RNF43." (PMID 36319622, 2022). "Finally, PORCN inhibition significantly suppressed PDX tumor development of RNF43‐mutant CRC cells, suggesting that PORCN inhibitors are an effective therapeutic strategy against RNF43‐mutant CRC development and metastasis." (PMID 35040131, 2022). "Finally, treatment with the PORCN inhibitor significantly suppressed RNF43‐mutant cell‐derived PDX tumor development." (PMID 35040131, 2022). "Several relevant genes have been associated with a high tumour mutational burden (including ARID1A, RNF43, BRAF and KM2B in microsatellite instability (MSI) cancers) and may help select MSS tumours for immunotherapy." (PMID 34694371, 2021). "As a tumor suppressor, RNF43 has shown its capacity to negatively regulate Wnt signaling." (PMID 34594355, 2021). "Importantly, doxycycline supplementation (RNF43 high) in addition to vemurafenib resulted in the more efficient suppression of tumor growth, suggesting the delayed the BRAFi resistance acquisition." (PMID 34702444, 2021). "The tumour without an RNF43 mutation harboured two truncal mutations in the APC tumour suppressor gene as an alternative mechanism of β-catenin activation." (PMID 31949146, 2020). "Thus, mislocalisation of RNF43(R127P) reduces RNF43-mediated ubiquitination of Fzd5, and the 3SD phosphomimetic substitution can restore the ubiquitination and tumour suppressor activity to RNF43(R127P)." (PMID 32934222, 2020). "Our findings suggest that therapeutic phosphomimetics could revert an oncogenic RNF43 mutant to a functional tumour suppressor." (PMID 32934222, 2020). "In contrast, the recovery of RNF43 activity by targeting serine phosphorylation could be a potential approach for tumour suppression with milder side effects, since it is predicted to only affect RNF43 mutant cells." (PMID 32934222, 2020). "Examples include mutations in RNF43 or PMS2, which could mark clonal subtypes that may make the tumor responsive to specific agents, such as checkpoint inhibitors." (PMID 31254442, 2019). "This same tumor also had six variants of uncertain significance: ARID2 c.1672C > T p.(R558C), FLT3 c.2546G > A p.(R849H), IGF1R c.3897C > G p.(N1298K), MSH6 c.1157C > G p.(P386R), PBRM1 c.2504G > A p.(R850H), and RNF43 c.1114C > T p.(P372S)." (PMID 31046843, 2019). "However, other events distinguish the two tumor types, with primary MOC carrying ERBB2 amplifications and RNF43 mutations, whereas pancreatic tumors show frequent SMAD4 alterations." (PMID 31477716, 2019). "Nevertheless, pathology did not progress to neoplasia, indicating that mutations in RNF43 alone are not sufficient to drive malignant transformation." (PMID 30884828, 2019). "Although the significance of higher RNF43 expression in our cases still unknown, tumor specific expression of RNF43 was considered to be a reliable target for immune therapy." (PMID 29293510, 2018). "Characteristics of RNF43 and immunohistochemical analysis in tumor biopsies." (PMID 29293510, 2018). "We successfully showed that the combination of immune cell therapy and CPA was safe, might induce tumor-specific immune responses and clinical efficacy, and was accompanied by a decreased ratio of Tregs in patients with RNF43-positive advanced solid tumors." (PMID 29293510, 2018). "We targeted tumor cells expressing relatively high levels of RNF43 without major gene mutations, possibly included in MSS tumors." (PMID 29293510, 2018).
tumor (continued). "Therefore, RNF43 is considered a valid target for anti-tumor, immunotherapeutic treatment and the combination with DC vaccination is expected to synergistically increase the antitumor immunity targeting RNF43." (PMID 29293510, 2018). "Furthermore, adenovirus-induced RNF43 OE inhibited tumor growth and stem cell-like phenotype through the canonical Wnt/β-catenin pathway both in vitro and in vivo." (PMID 28446252, 2017). "However, whether these mutants are completely normal and fully retain the original function as a tumor suppressor remains unclear because RNF43 may be involved in other signaling pathways that affect tumorigenesis." (PMID 38383910, 2024). "In summary, although our germline analyses did not reveal a potential explanation for tumor multiplicity in our LS individuals, we describe a non-random association of RNF43 hotspot variants to hypermethylator tumor phenotype that is distinct from the classical BRAF V600E-associated CIMP." (PMID 38725616, 2024). "The single tumor of LS-202 with enough DNA for testing did not carry any RNF43 hotspot mutations." (PMID 38725616, 2024). "RNF43 encodes a transmembrane protein with ubiquitin E3 ligase activity and its N-terminal domain can induce ubiquitination of frizzled receptor 5 (FZD5), thereby inhibiting the FZD5 receptor-dependent Wnt signaling cascade and exerting a tumor suppressor effect." (PMID 37304241, 2023). "However, Rnf43 knockdown abolished the efficacy against CTAG1B-overexpressing tumours." (PMID 36732592, 2023). "Similarly, Rnf43-knockdown tumours (RENCA), generated using shRNA, were resistant to PD-1 blockade." (PMID 36732592, 2023). "Even though the loss of Rnf43 led to bigger pancreata, this was not sufficient to cause tumor." (PMID 35229994, 2022). "RNF43 and AXIN2 are negative regulators of the Wnt-ligand dependent type of CRC and their downregulation in MSI samples might suggest an association of Wnt ligand dependent pathogenesis in a subset of tumours." (PMID 34824625, 2021). "Similarly, terminally differentiated enterocytes or DCLK1+ tuft-cells re-express ISC markers (Lgr5, Ascl2, Rnf43) and acquire tumour-forming capacity following simultaneous stimulation of Wnt and inflammation pathways, which support a ‘top-down’ model of CRC initiation." (PMID 29570681, 2018). "As we could detect no major ZNRF3/RNF43 gene mutations in our patients' tumor, the latter might be functional in our cases." (PMID 29293510, 2018). "The RCOR2/LSD1 sub-axis suppresses RNF43 transcription to activate Wnt/β-catenin signaling in tumor cells, whereas the RCOR2/HDAC1/2 sub-axis inhibits CIITA and MHC-II expression in tumor cells to block activation of CD4+ and CD8+ T cells." (PMID 40608411, 2025). "Mechanistically, RCOR2 repressed RNF43 expression through LSD1-mediated demethylation of histone H3 at lysine 4 to induce activation of Wnt/β-catenin and tumor stemness." (PMID 40608411, 2025). "As both BRCA1 and RNF43 reside on chromosome 17q, the LOH observed across the region encompassing both these tumor suppressor genes confirms that both BRCA1 and RNF43 had biallelic inactivation." (PMID 38063999, 2024).
tumor (continued). "RNF43-derived peptides of TAA were tested for the induction of cytotoxic T-lymphocytes (CTLs) and CD8+ T cells, specific for tumor cells." (PMID 39125653, 2024). "IHC demonstrated that Rnf43 knockdown impaired DC and CD8+ T cell infiltration even in CTAG1B-overexpressing tumours." (PMID 36732592, 2023). "IHC revealed that human RNF43 117fs-overexpressing tumours had a lesser DC and CD8+ T cell infiltration than human RNF43 WT-overexpressing tumours, which is consistent with a previous study and the results of our in vitro analysis." (PMID 36732592, 2023). "However, tumours with RNF43 mutations did not always have an inflamed TME." (PMID 36732592, 2023). "Both RNF43 and LRP1B function as tumor suppressors in the Wnt signaling pathway and have been described to be frequently mutated in GC." (PMID 36823311, 2023). "In RNF43‐mutant PDAC, the cholesterol level governs tumor growth through Fzd5‐mediated Wnt/β‐catenin signaling in vitro and in vivo." (PMID 35975457, 2022). "In our study, we demonstrated that miR-181d-5p played an oncogenic role by suppressing RNF43 and activating Wnt/β-catenin signal in RCC, thus promoting cancer stemness and tumor progression." (PMID 36319622, 2022). "Studies have demonstrated that AHR signalling maintains normal ISC proliferation by promoting Znrf3 and Rnf43 expression to suppress aberrant WNT-β-catenin signalling and tumour progression." (PMID 36555220, 2022). "Our study suggested that, like RNF43 and RNF20, RNF38 plays a tumor-suppressing role in NPC and is supposed to be a potential biomarker for predicting recurrence and metastasis according to our study." (PMID 35568845, 2022). "RING finger protein 43 (RNF43) is an E3 ubiquitin ligase with demonstrated effect as an inhibitor of WNT signaling; studies have suggested its role in tumor suppression, by blocking the WNT pathway downstream of oncogenic mutations that activate the pathway." (PMID 35267592, 2022). "Ring finger protein 43 (RNF43), which has been described as both an oncogene and tumorsuppressor gene, was downregulated in tumor tissue of patients with iCCA and correlated with poor prognosis." (PMID 35205774, 2022). "Reduced tumor growth and increased cancer cell differentiation were observed in SNU-1411 (RSPO3-fusion), AsPC1 and HPAF-II (both RNF43-mutant) xenograft models, with a therapeutic window versus Wnt homeostatic functions." (PMID 36922934, 2022). "Mechanistically, exosomal miR-181d-5p transferred from CAFs to RCC cells directly suppressed the expression of ring finger protein 43 (RNF43) and activated Wnt/β-catenin signaling pathway, thus promoted cancer stemness and tumor progression." (PMID 36319622, 2022). "Their computed analysis of tumor infiltrating immune cells identified an increment in CD8+ T cells, M1, NK, and total T cells compared with the wild type RNF43 group." (PMID 36358851, 2022). "RNF43 (CEA level ≥ 5: 13.2%, CEA level < 5: 3.4%; p = 0.036) is known as a tumor suppressor and negatively regulates WNT signaling." (PMID 35003350, 2021). "It is interesting to note that, ETV4, RNF43 and AXIN2 are highly correlated with tumour cell purity." (PMID 34824625, 2021). "In conclusion, we found that RNF43-G659Vfs*41 was able to inhibit Wnt signaling as much as the WT enzyme could and that this mutation was most likely a passenger mutation due to error-prone replication of a seven G repeat in its open reading frame in MLH1-deficient tumor cells." (PMID 31811196, 2019). "ChIP qPCR of intestinal epithelial cells established Rnf43 as a direct target of AHR, suggesting that this tumor suppressor, which acts in a complex with ZNRF3, is transcriptionally regulated by AHR." (PMID 30119997, 2018).